NEDD8 (NEDD8 ubiquitin like modifier)
Diseases named in the same sentence as NEDD8 in open-access papers (continued):
Sharing a sentence is not in itself a finding about the gene and the disease.
tumor (48 papers, 2014 to 2026). "Negative regulator of ubiquitin-like protein 1 (NUB1), an inhibitor of neural precursor cells expressed developmentally downregulated 8 (NEDD8), is implicated in tumor growth." (PMID 40164590, 2025). "Consistent with earlier results, Nedd8 deficiency significantly improved response to PD-1 blockade and survival of tumor-bearing mice, which was abrogated with the depletion of CD8+ T cells." (PMID 38678024, 2024). "In contrast, we observe tumor regression mediated by CD8+ T cells against Nedd8 deficient EO771 tumors after PD-1 blockade." (PMID 38678024, 2024). "The NEDDylation pathway was excessively activated in many human tumor tissues compared with adjacent normal tissues, and the overexpression of enzymes associated with NEDD8 NEDDylation was associated with disease progression." (PMID 35880551, 2022). "The multivariate analyses indicated that higher NEDD8 expression, together with positive HBsAg, positive HBeAg, larger tumor size, and poorer BCLC stage, was an independent risk factor for both OS and RFS." (PMID 29846044, 2018). "NUB1 was initially identified as a negative regulator of NEDD8 and was confirmed to be expressed in various tumor cell lines." (PMID 40164590, 2025). "Further mechanistic investigations using advanced human cell assays and syngeneic mouse models confirm the strong immunogenic effects and anti-tumor efficacy as a result of Nedd8 deletion in ICB-treated TNBC cells." (PMID 38678024, 2024). "In recent years, the role of NEDD8-driven neddylation in tumor development has drawn considerable attention." (PMID 38177106, 2024). "Based on these findings, we conclude that NEDD8/neddylation is a crucial regulatory mechanism of elevated Treg immunosuppression upon surgical stress, which leads to defective anti-tumor immunity and, finally the postoperative metastasis." (PMID 38177106, 2024). "In contrast, PD-1 blockade resulted in highly significant tumor growth delay (p < 0.0001) in all mice bearing Nedd8 KO EO771 tumors." (PMID 38678024, 2024). "Because NEDD8 is widely expressed by many cell types in the tumor micro-environment, single-cell RNA sequencing datasets in a large cohort of TNBC patients are needed to validate the clinical relevance of our findings." (PMID 38678024, 2024). "These phenotypes are associated with the resulting increased cell contractility, a process also required for the anti-invasive effect of NEDD8 inhibition in metastatic tumour cells." (PMID 39404389, 2024). "In TICS, NEDD8 KO cells strongly enhance immune activation and result in anti-tumor effects after PD-1 blockade in tumor-bearing mice." (PMID 38678024, 2024). "Recent reports have demonstrated that NEDD8 promotes tumor progression and predicts a poor prognosis in patients with colorectal cancer, nasopharyngeal carcinoma and bladder cancer." (PMID 36890567, 2023). "Next, they verified the findings by analyzing NEDD8 expression in tumor-infiltrating macrophages derived from colorectal cancer (CRC) mouse models treated with CD47 blockade or a control agent." (PMID 36787255, 2023). "They first showed that the process of neddylation and NEDD8 expression were increased in various cancer types in SIRPα+ tumor-infiltrating macrophages." (PMID 36787255, 2023). "Confirmation of the interplay between the CD47/SIRPα pathway and NEDD8 was substantiated by decreased deneddylation in CD68+ macrophages from tumor tissue organoids treated with anti-CD47 antibody." (PMID 36787255, 2023). "We then created a prognostic model demonstrating that low levels of NEDD8 and TOP1 expression in tumor tissues are associated with a favorable prognosis (p < 0.01)." (PMID 37689760, 2023). "Elevated expression of NEDD8 was then observed in various human tumor cell lines, including leukemia cells and HeLa." (PMID 35602593, 2022). "Our results showed that downregulation of NEDD8 activated a series of biological tumor-suppressive processes." (PMID 33733647, 2021).
tumor (continued). "In vivo experiments further showed that downregulation of NEDD8 significantly repressed ESCC tumor growth." (PMID 33733647, 2021). "Collectively, our results indicated that knockdown of NEDD8 leads to CRLs inactivation and the accumulation of tumor-suppressive CRL substrates, thus inhibiting tumor growth in vivo." (PMID 33733647, 2021). "To investigate the therapeutic potential of NEDD8 silencing in vivo, we established a subcutaneous-transplantation tumor model using NEDD8-knockdown EC1 cells." (PMID 33733647, 2021). "We previously showed that the NEDD8 pathway inhibitor pevonedistat induced tumor stabilization in preclinical models of aggressive CRC." (PMID 34359705, 2021). "Downregulation of NEDD8 significantly inhibited tumor growth, according to the tumor growth curve (P < 0.001)." (PMID 33733647, 2021). "A subcutaneous-transplantation mouse tumor model was established to investigate the anticancer potential of NEDD8 silencing in vivo." (PMID 33733647, 2021). "Last but not least, several reports have demonstrated that in multiple cancers the neddylation pathway is overactivated and NEDD8-conjugated proteins are overexpressed, leading to the degradation of many tumor suppressor substrates of CRLs." (PMID 32272761, 2020). "Collectively, the presented data suggest that the levels of Mdmx in tumours may be a critical determinant for the efficacy of NEDD8 inhibitors in the clinic through control of RhoA stability/activity." (PMID 39404389, 2024). "The role of NEDD8-mediated neddylation in tumor progression has already been recognized." (PMID 38177106, 2024). "As inhibitors of the NEDD8 pathway are in clinical trials, the status of Mdmx may be a critical determinant for the anti-tumour effects of these inhibitors." (PMID 39404389, 2024). "None of the mice bearing control EO771 tumors responded to PD-1 blockade and Nedd8 deficiency did not delay tumor growth when treated with the isotype control antibody, as compared to mice bearing control tumors." (PMID 38678024, 2024). "Likewise, our data reported a distinctive NEDD8 expression pattern of tumor-infiltrating myeloid cells in CRC." (PMID 36626230, 2023). "Moreover, MLN4924 leads to impaired NEDD8-dependent clearance of misfolded proteins and an altered tumor immune microenvironment due to increased numbers of cytotoxic T cells and conventional CD4+ T cells and decreased numbers of regulatory T cells." (PMID 36910623, 2023). "In these particular tumor types, it would appear that increased levels of NEDD8 and/or decreased levels of UBA1 are present and could in fact be representative of the conditions used to isolate NEDDylated proteins in vitro." (PMID 34685640, 2021). "Moreover, compared with the control group mice, which developed 100% (7/7) large tumors, only 71.4% (5/7) of the NEDD8-knockdown group mice developed small tumors; these results were further supported by tumor weight assessment (P < 0.001)." (PMID 33733647, 2021). "Interestingly, the authors found that NEDP1 was down-regulated in a moue model of hepatocellular carcinoma suggesting that in tumors, the increased levels of NEDD8 chains on HSP70 prevents tumor cell apoptosis." (PMID 34685640, 2021). "Downregulation of NEDD8 significantly suppressed tumor growth both in vitro and in vivo." (PMID 33733647, 2021). "Furthermore, genetic downregulation of NEDD8 profoundly suppresses ESCC tumor growth by triggering cell cycle arrest, DNA damage, and apoptosis." (PMID 33733647, 2021). "For instance, Von Hippel-Lindau (VHL) modification by NEDD8 is significant for tumor suppression." (PMID 33097763, 2020). "Moreover, decreased tumor size in the MLN4924-treated group was associated with a down regulation of global neddylation, observed by decreased Nedd8-cullin conjugates and, of the already known Nedd8 target, HuR." (PMID 25650664, 2015).
tumor (continued). "Here we report that NEDD8 expression is significantly higher in HNSCC compared to adjacent normal tissue suggesting that targeting NEDDylation may be a novel approach to treat this tumor type." (PMID 35428778, 2022). "Our previous study has demonstrated that FKA inhibited NEDD8 conjugations to both Cullin1 and Ubc12, delayed tumor progression, and eliminated distant metastasis in the TRMAP transgenic mouse model, although it was unclear whether the underlying mechanism was related to the inhibition of CSCs." (PMID 35912174, 2022). "Neddylation is a process that conjugates a ubiquitin-like molecule NEDD8 (neuronal precursor cell-expressed developmentally down-regulated protein 8) to a lysine residue of the substrate protein and regulates many stages of tumor development including tumorigenesis and metastasis." (PMID 33184273, 2020). "An exception to this trend was PIM172, which showed comparable levels of NEDD8 and SUMO1 to those tumor models that responded robustly to pevonedistat in vivo." (PMID 38802426, 2024). "Given the identification of both neddylation and sumoylation pathways in our transcriptomic analyses, we conducted immunohistochemistry to assess levels of NEDD8 and SUMO1 in PDX tumor samples." (PMID 38802426, 2024). "Our data also showed that NEDD8 deletion alone increased the frequency of CD8+T cells and NK cells, which indicates enhanced anti-tumor activity." (PMID 38177106, 2024). "Inhibiting NEDD8, a ubiquitin-like protein, with MLN4924 also shows antitumor promise by promoting apoptosis and blocking tumor growth in preclinical models." (PMID 39590345, 2024). "Our data indicated that MLN4924 significantly inhibited AB's anti-tumor effects both in vitro and in vivo, underscoring the importance of the ubiquitination pathway mediated by TRIM4 and NEDD8 neddylation in TNBC progression." (PMID 39629122, 2024). "NEDDylated PTEN has been detected in breast cancer cells lines and NEDD8 conjugation to PTEN allows for nuclear localization and promotes tumor growth." (PMID 34685640, 2021). "Furthermore, high expression of neural precursor cell expressed, developmentally downregulated 8 (NEDD8) enhances autophagy activation by inhibiting the PI3K/AKT/mTOR pathway, significantly increasing tumor cell radioresistance." (PMID 40725100, 2025). "Specifically, NEDD8 overexpression elevates protein levels of autophagy-related molecules Beclin-1, Autophagy-related gene 5 (ATG5), and LC3-II, whereas NEDD8 knockdown reduces these molecules’ expression and markedly decreases tumor cell radioresistance." (PMID 40725100, 2025). "Furthermore, inhibiting the ubiquitin-like protein NEDD8 with MLN4924 has shown promising antitumor effects by reducing cell proliferation and enhancing apoptosis, even inhibiting tumor growth in xenograft models." (PMID 39590345, 2024). "Thus, MLN4924 inhibited the NEDD8 NEDDylation to inactivate CRLs, leading to the accumulation of CRL substrates and ultimately inhibiting tumor growth." (PMID 35880551, 2022). "As inhibitors for the NEDD8 pathway are in phase II clinical trials, NEDP1 levels may provide a marker for the tumor response to these inhibitors." (PMID 31577950, 2019). "The specificity of the thalidomide effect is further underscored by our observation that PMA (phorbol myristate acetate, or 12-0-tetradecanoyl-phorbol-13-acetate) (10 nM) a tumor-promoting ester treatment attenuated CUL5 but not NEDD8 signal intensity." (PMID 29746508, 2018). "Moreover, renal biopsies from patients with biopsy-proven DN exhibited elevated NAE1 and NEDD8 expression levels compared with normal kidney tissues obtained from tumor nephrectomy patients without renal disease." (PMID 39900822, 2025). "For any clinical development, it will be important to identify biomarkers predictive of response, which could start with further exploration of NEDD8 and SUMO1 protein levels in tumor tissues based on the results in our PDX models, and to explore mechanisms of pevonedistat resistance." (PMID 38802426, 2024).
tumor (continued). "Although NEDD8, NAE1, and UBC12 expression significantly correlated with tumor recurrence, their expression intensities were largely independent of conventional clinicopathologic features, like tumor size, vascular invasion, lymph node metastasis, intrahepatic metastasis and TNM stage." (PMID 25229838, 2014). "Of note, subgroup analysis showed that the prognostic value of NEDD8, NAE1, and UBC12 also existed in patients with relatively early stage disease, such as patients with small tumor, or with no vascular invasion, or in early TNM stages (I+II)." (PMID 25229838, 2014).
infection (11 papers, 2010 to 2026). The state of being infected such as from the introduction of a foreign agent such as serum, vaccine, antigenic substance or organism. "To substantiate this hypothesis, we performed P. yoelii 17XNL infection in another conditional knockout model with a T cell-specific deficiency of NEDD8 (Nedd8fl/flLck-Cre+, named as Nedd8ΔT mice)." (PMID 30462731, 2018). "To avoid mistakenly identifying ubiquitin or NEDD8 sites as ISG15 sites (due to possible indirect effects of Isg15 deletion or USP18C61A/C61A mutation), we assessed whether ubiquitin and NEDD8 levels appear to vary using SDS-PAGE prior to or following infection." (PMID 31772204, 2019). "These unique multifaceted deconjugating activities against SUMO, ubiquitin, and Nedd8 exemplify an optimized bacterial protease that disrupts distinct UbL post-translational modifications during host cell infection." (PMID 38802699, 2024). "Firstly, we examined accumulation of LsCUL1 in healthy or BY-RFP-infected SBPHs, and showed that BY-RFP infection led to significantly increased ratio of CUL1Nedd (CUL1 with Nedd8 moiety) to CUL1, indicating that BY-RFP interfered with de-neddylation of CUL1." (PMID 37717061, 2023). "The function of ubiquitin-like moieties, such as neural precursor cell-expressed developmentally downregulated protein 8 (NEDD8), in alphaherpesvirus entry and infection is incompletely understood and is a focus of the current report." (PMID 36173301, 2022). "To interrogate further the proteasomal mechanism of entry, we determined the involvement of the ubiquitin-like molecule NEDD8 and the neddylation cascade in alphaherpesvirus entry and infection." (PMID 36173301, 2022). "In vitro total ubiquitin did not dramatically change in mouse embryonic fibroblasts 24 h post infection, whereas NEDD8 was slightly reduced." (PMID 31772204, 2019). "In parallel with the observations in vitro, T cells expressed dramatically increased amounts of Uba3 and NEDD8-conjugated proteins within 5 days of the infection, confirming activation of neddylation in parasite-responsive T cells." (PMID 30462731, 2018). "Here, we have shown that Cif binds to NEDD8 and neddylated cullins, inducing their accumulation early after infection." (PMID 20941356, 2010). "We show that Cif binds to NEDD8 and induce accumulation of neddylated cullins early after infection." (PMID 20941356, 2010). "In a second experiment, it was shown that the inhibition of modification with NEDD8 (NEDDylation) (with MLN4924) also results in the stabilization of Tab182 following Ad5 and Ad12 infection." (PMID 29593045, 2018). "Consistent with P. yoelii 17XNL infection, immunoprecipitates from 293 T cells over-expressed with Myc-tagged Itch confirmed NEDD8 conjugation with Itch, which was almost completely absent by addition of MLN4924." (PMID 30462731, 2018). "The existence of a deconjugating protease, such as rhizobia NopD, which is simultaneously active for ubiquitin, Nedd8 and SUMO is quite uncommon, and represents a paradigmatic example of an optimized catalytic domain containing multiple UbL deconjugating activities during host infection." (PMID 38802699, 2024).
Head and neck tumors (2 papers, 2022). "Head and neck tumors were found to significantly overexpress NEDD8 when compared to normal adjacent tissue (p = 0.0076), thus establishing the rationale for exploring targeted inhibition of NEDDylation as an approach for HNSCC therapy." (PMID 35428778, 2022).
cardiovascular disease (1 paper, 2016). "TTYH2 and NEDD8 may play a role in the genetic architecture of cardiovascular disease, blood pressure regulation, and other disorders." (PMID 26752167, 2016).
neurodegenerative disease (1 paper, 2025). A disorder of the central nervous system characterized by gradual and progressive loss of neural tissue and neurologic function. "NEDD8 has been detected within ubiquitin-positive inclusions in several neurodegenerative diseases including ALS, ALS/FTD, PD, and Alzheimer’s disease." (PMID 40764342, 2025).
NEDD8 also shares sentences with these, for which no sentence is quoted: intrahepatic cholangiocarcinoma (3 papers); lung adenocarcinoma (2); oral squamous cell carcinoma (2); acute lymphoblastic leukemia (1); acute myeloid leukemia (1); adenocarcinoma (1); amyotrophic lateral sclerosis (1); antiphospholipid syndrome (1); brain disease (1); cholangiocarcinoma (1); diffuse large B-cell lymphoma (1); Down syndrome (1); glioma (1); hematological malignancies (1); hematopoietic cancers (1); lung squamous cell carcinoma (1); Lynch syndrome (1); mild cognitive impairment (1); ovarian tumor (1); renal carcinoma (1); renal disease (1); rheumatoid arthritis (1); systemic lupus erythematosus (1); triple-negative breast carcinoma (1); Venous thrombosis (1); α-Synucleinopathy (1).